UGT1A1 (UDP glucuronosyltransferase family 1 member A1)
Diseases named in the same sentence as UGT1A1 in open-access papers (continued):
Sharing a sentence is not in itself a finding about the gene and the disease.
colitis (7 papers, 2017 to 2024). Inflammation of the colon. "Downregulation of PXR in colitis is associated with dampened UGT1A1 and UGT1A9, thereby potentially resulting in dysfunction of flavonoid glucuronidation." (PMID 36408246, 2022). "Dysregulation of PXR in colitis is associated with the downregulation of UGT1A1 and UGT1A9, thereby potentially resulting in dysfunction of baicalein and puerarin glucuronidation." (PMID 36408246, 2022). "Taken together, these findings indicate that deregulation of PXR in colitis is associated with the downregulation of UGT1A1 and UGT1A9, thereby potentially resulting in dysfunction of flavonoid glucuronidation." (PMID 36408246, 2022). "In the current study, we observed that the downregulation of PXR in colitis is associated with suppressed UGT1A1 and UGT1A9." (PMID 36408246, 2022). "Disturbance of hepatic and intestinal UGTs (e.g., UGT1A1 and 1A6) in rats was observed in trinitrobenzene sulfonic acid-induced colitis." (PMID 36408246, 2022). "OMVs secreted by intestinal microbes from colitis rats can down-regulate UGT1A1 expression in Caco-2 cells through a macrophage-mediated mechanism, thus causing intestinal ecological imbalance." (PMID 36611884, 2022). "We thus established a DSS-induced colitis model to determine the effects of colitis on UGT1A1 and UGT1A9 in various tissues." (PMID 36408246, 2022). "PXR was the only UGT regulator significantly downregulated in colitis mice, suggesting dysregulation of PXR is associated with the downregulation of UGT1A1 and UGT1A9, thereby potentially resulting in dysfunction of baicalein and puerarin glucuronidation." (PMID 36408246, 2022). "We thus investigated how these nuclear receptors mediate colitis-regulated UGT1A1 and UGT1A9 in the liver." (PMID 36408246, 2022). "Twelve UGTs were downregulated in the liver of colitis mice including UGT1A1 and UGT1A9 (two representative UGTs)." (PMID 36408246, 2022). "Secondly, Ugt1a1 and Ugt1a9 are consistently suppressed in the Il-10−/− spontaneously develop colitis mice as compared to the control mice." (PMID 36408246, 2022). "Moreover, we observed that colitis-reduced UGT1A1 and UGT1A9 led to dampened baicalein and puerarin glucuronidation." (PMID 36408246, 2022). "Moreover, colitis-reduced UGT1A1 and UGT1A9 lead to dampened baicalein and puerarin glucuronidation." (PMID 36408246, 2022). "We confirmed that protein expression of UGT1A1 and UGT1A9 were consistently suppressed in the liver of colitis mice." (PMID 36408246, 2022). "Altogether, downregulation of hepatic UGT1A1 and UGT1A9 in colitis leads to dampened flavonoid glucuronidation." (PMID 36408246, 2022). "Therefore, the inhibitory effects of colitis on UGT1A1 and UGT1A9 could be time-varying." (PMID 36408246, 2022). "In dextran sulfate sodium- (DSS-) induced colitis, the gut microbiota regulate intestinal UDP-glucuronosyltransferase 1A1 (UGT1A1) through secreting cargo that can interact with epithelial cells directly." (PMID 32410847, 2020). "Firstly, 1 day of DSS administration is insufficient to induce colitis and does not alter the expression of Ugt1a1 and Ugt1a9." (PMID 36408246, 2022). "In addition, UGT1A1 and UGT1A9 were downregulated in a genetic colitis model (Il-10−/− spontaneously develop colitis), which is in accordance with the results of the DSS-induced colitis model." (PMID 36408246, 2022). "Colitis in mice downregulated UGT1A1 and UGT1A9 in the liver but not in small intestine, colon, and kidney." (PMID 36408246, 2022). "Among the UGT1A1 and UGT1A9 regulators, only Pxr was significantly downregulated in colitis mice, suggesting dysregulation of PXR in colitis is associated with the downregulation of UGT1A1 and UGT1A9, thereby potentially resulting in dysfunction of baicalein and puerarin glucuronidation." (PMID 36408246, 2022). "They observed a decrease of gut UGT1A1 protein concentration in rats with colitis, confirming the negative correlation between metabolic capacity and inflammation." (PMID 31810282, 2019).
colitis (continued). "After, they also reported a decrease of UGT1A1 gene expression in a condition of gut dysbiosis induced by Gram-negative bacteria, both in normal and colitis rats, showing a possible relevant role of microbiota in xenobiotic metabolizing enzymes expression regulation." (PMID 31810282, 2019). "Colitis in mice downregulates UGT1A1 and UGT1A9 in the liver but not in other metabolic tissues, indicating colitis-induced dysregulation pattern of UGTs is specifically occurring in the liver." (PMID 36408246, 2022).
G6PD deficiency (7 papers, 2015 to 2023). An X-linked genetic condition caused by alterations in the gene G6PD that result in moderately to severely decreased activity levels of the enzyme glucose-6-phosphate dehydrogenase. "Heterozygosity to 6/7 TA repeats in the promoter of UGT1A1 was associated with more significant neonatal jaundice, especially if the newborn infant had complete or partial G6PD deficiency." (PMID 37508669, 2023). "Population attributable risks (PAR%) were 61.7% for lower gestational age, 22.9% for hemi or homozygous and 9.9% for heterozygous G6PD deficiency respectively, and 6.3% for UGT1A1*6 homozygosity." (PMID 36962413, 2022). "The six neonatal factors with sufficient data for the meta-analysis were G6PD deficiency, UGT1A1 polymorphisms, gestational age, weight on admission, sepsis and TcB/TSB levels." (PMID 25675342, 2015). "However, it seems that the interaction between G6PD deficiency, UGT1A1 promoter polymorphism, and NHB is more complex, possibly involving other genetic interactions, not yet described." (PMID 37508669, 2023). "Heterozygosity to 6/7 TA repeats in the UGT1A1 promoter was associated with increased NHB, especially in female newborns with G6PD deficiency." (PMID 37508669, 2023). "In summary, it is important to continue performing more studies to evaluate the role of genetic screening with analysis of the number of TA repeats in the UGT1A1 promoter to assess for increased risk for NHB, especially in heterozygous females to G6PD deficiency." (PMID 37508669, 2023).
Hypertension (7 papers, 2017 to 2023). The presence of chronic increased pressure in the systemic arterial system. "Genetic variations in Ugt1a1 are associated with elevated bilirubin and an increased risk of hypertension in individuals with African ancestry." (PMID 36760467, 2023). "Genetic variants VEGFR2 rs2239702, ABCB1 rs1045642 and ABCB1 rs2032582 were significantly associated with increased risk of HFS and hypertension; ABCB1 rs1128503 was reported associated with increased risk of hypertension; UGT1A1*6 rs4148323 and UGT1A9 were associated with hypertension." (PMID 28404979, 2017). "Mice made moderately hyperbilirubinemic via antagonism of hepatic UDP-glucuronosyltransferase 1-1 (UGT1A1) are resistant to Ang II-induced hypertension and decreases in renal blood flow and glomerular filtration rate (GFR)." (PMID 31216709, 2019). "For example, previous translational data have suggested the involvement of the hemochromatosis gene (HFE) and UGT1A1 polymorphisms in hepatic enzyme elevation with pazopanib and vascular endothelial growth factor (VEGF) polymorphisms with hypertension effects of sunitinib." (PMID 29788981, 2018).
coronary artery disease (6 papers, 2009 to 2022). "al. utilized genotype at the UGT1A1*28 locus to suggest a causal role for bilirubin in cardiovascular and coronary heart diseases." (PMID 22416852, 2012). "Recently, a promoter variation (UGT1A1*28) has been associated with higher bilirubin serum levels and lower risk for coronary heart disease in the Framingham Heart Study." (PMID 19389234, 2009). "There are few studies on the effect of bilirubin levels and/or of UGT1A1 gene polymorphism in the outcome of CVD in the general population, namely, in the development of coronary artery disease, coronary heart disease, peripheral vascular disease, and stroke." (PMID 25276769, 2014).
Hepatic steatosis (6 papers, 2013 to 2023). Steatosis is a term used to denote lipid accumulation within hepatocytes. "Mice on high-fat and high-sucrose diet, which develop severe hepatic steatosis, display elevated expression of Ugt1a1 and Ugt1a6 mediated by CAR and PXR." (PMID 23346097, 2013). "However, the relationship between circulating UGT1A1 levels and hepatic steatosis remains unclear." (PMID 34986792, 2022).
leukopenia (6 papers, 2004 to 2025). "The results showed that UGT1A1*28 wild type (TA6/6) had a higher incidence of grade 0–2 leukopenia than mutant type (TA6/7 + TA7/7) [RR = 1.17, 95%CI (1.02, 1.35), P = 0.03], and the results were statistically different." (PMID 40170723, 2025). "In this analysis, additional genotyping for the UGT1A1*27 polymorphism was also done, because previous studies have reported that Japanese cancer patients heterozygous for UGT1A1*27 experienced severe diarrhea or leukopenia." (PMID 36239106, 2022). "Patients with UGT1A1 polymorphisms showed a higher frequency of grade 4 leukopenia, but these patients did not have increased treatment‐related mortality or non‐hematologic toxicity." (PMID 35233973, 2022). "In our study, patients with UGT1A1 polymorphisms had an increased frequency of grade 4 leukopenia after IREC therapy but had no increase in FN or BSI compared with wild‐type patients." (PMID 35233973, 2022). "They reported a frequency of the UGT1A1*28 allele 3.5-fold higher in patients with toxicity (severe diarrhoea or leukopenia) compared with patients without this complication (P<0.0001)." (PMID 15280927, 2004). "In summary, the polymorphisms of UGT1A1*28 gene were associated with the incidence of leukopenia in cancer patients during IRI chemotherapy, and the incidence of wild type (TA6/6) was higher in mild leukopenia, and the incidence of mutant type (TA6/7 + TA7/7) was higher in severe leukopenia." (PMID 40170723, 2025).
sickle cell anemia (6 papers, 2012 to 2022). "Allele and genotype frequencies of UGT1A1 promoter polymorphism in β-Thalassemia, Sickle Cell Anemia and Healthy Controls (# total Bilirubin measured in μmol/L)." (PMID 24204915, 2013). "Serum bilirubin levels have been associated with polymorphisms in the UGT1A1 promoter in normal populations and in patients with hemolytic anemias, including sickle cell anemia." (PMID 22558097, 2012). "In summary, SNPs in UGT1A1 are most tightly associated with bilirubin levels in African Americans with sickle cell anemia." (PMID 22558097, 2012).
Thrombocytopenia (6 papers, 2014 to 2025). A reduction in the number of circulating thrombocytes. "Those harboring UGT1A1 *28 or *60 alleles also experienced higher grade thrombocytopenia and elevated QTc intervals when compared to patients without UGT1A1 polymorphisms." (PMID 33805415, 2021). "Moreover, ERCC2 rs1799793 (p = 0.03 in a dominant model) and UGT1A1 rs3064744 (p = 0.03 in a recessive model) were significantly associated with thrombocytopenia." (PMID 39339159, 2024). "In summary, the polymorphism of UGT1A1*28 gene was associated with the incidence of severe thrombocytopenia in cancer patients during IRI chemotherapy, and the incidence of mutation (TA6/7 + TA7/7) was higher in severe thrombocytopenia." (PMID 40170723, 2025).
type 2 diabetes (6 papers, 2015 to 2024). "The study found that a common genetic variant (rs6742078) of the UGT1A1 gene, which is involved in bilirubin metabolism, was strongly associated with an increase in the circulating level of total bilirubin and a decrease in the risk of type 2 diabetes." (PMID 38195551, 2024). "In both male and female type 2 diabetes-induced Sprague–Dawley rats treated with streptozotocin, consumption of a high-fat diet increased UGT1A1, UGT1A6, and UGT1A7 probe activities but decreased the UGT2B1 probe activity." (PMID 37034183, 2023). "The aim of this study was to assess serum bilirubin concentrations and (TA)n and (GT)n microsatellite variations in the promoter regions of the UGT1A1 and HMOX1 genes, respectively, in patients with type 2 diabetes mellitus (T2DM)." (PMID 37445792, 2023).
Stroke (5 papers, 2019 to 2023). Sudden impairment of blood flow to a part of the brain due to occlusion or rupture of an artery to the brain. "We did not observe any association between the UGT1A1 (TA) n genotypes and any of the other SCA downstream events/phenotypes examined (VOC, leg ulcer, priapism, overt stroke and osteonecrosis) that could be perturbed by both inflammatory and oxidative injuries in SCA." (PMID 31619193, 2019).
Cirrhosis (4 papers, 2021 to 2025). A chronic disorder of the liver in which liver tissue becomes scarred and is partially replaced by regenerative nodules and fibrotic tissue resulting in loss of liver function. "The incidence of cirrhosis or hepatocellular carcinoma (LC/HCC) was significantly lower in UGT1A1 variant hosts than in UGT1A1 wild-type hosts (13.14% vs." (PMID 38028601, 2023). "The relative abundance of UGT1A1 was, however, higher inmild and severe stages of cirrhosis compared with that in the controlsas it is barely affected by the disease." (PMID 34428046, 2021). "On the contrary, for UGTS, UGT1A1 ranked fifth in the controlgroup and second in the mild and severe cirrhosis groups." (PMID 34428046, 2021). "In contrast, patients without cirrhosis achieving HBsAg clearance were identified only in the UGT1A1 variant group (12.32% vs. 0%)." (PMID 38028601, 2023).
COVID-19 (4 papers, 2022 to 2025). A disease caused by infection with severe acute respiratory syndrome coronavirus 2. "This study demonstrates a significant association between reduced DNA methylation at the UGT1A1 locus and persistent anosmia in COVID-19 patients." (PMID 39767184, 2024). "In this study, we aimed to investigate epigenetic alterations in the form of DNA methylation in the UGT1A1 gene, which is a locus associated with olfactory dysfunction in COVID-19 patients." (PMID 39767184, 2024). "A significant decrease in methylation of the locus tested, towards the end of intron 1 in the gene UGT1A1, was found in COVID-19 patients who had lost their sense of smell." (PMID 39767184, 2024).
diabetes (4 papers, 2016 to 2024). "The results indicated that the pathological state of diabetes could significantly increase the mRNA and protein levels of Ugt1a1 and Ugt1a7 in rats." (PMID 29925761, 2018).
Dubin-Johnson syndrome (4 papers, 2019 to 2026). Dubin-Johnson syndrome (DJS) is a benign, inherited liver disorder characterized clinically by chronic, predominantly conjugated, hyperbilirubinemia and histopathologically by black-brown pigment deposition in parenchymal liver cells. "For example, patients with genetic hyperbilirubinemias such as Dubin-Johnson syndrome, a disorder involving mutations in the bilirubin transporter ABCC2, or Crigler-Najjar Type 1, a disorder involving mutations in the bilirubin glucuronosyltransferase UGT1A1, rarely complain of pruritus." (PMID 30657454, 2019).
esophageal cancer (4 papers, 2021 to 2024). A primary or metastatic malignant neoplasm involving the esophagus. "UGT1A1 and UGT2B7 expression that were recently reported in esophageal cancer tissues." (PMID 36295907, 2022).
leukemia (4 papers, 2008 to 2024). A malignant (clonal) hematologic disorder, involving hematopoietic stem cells and characterized by the presence of primitive or atypical myeloid or lymphoid cells in the bone marrow and the blood. "A research has demonstrated that UGT1A1 mutations in pediatric leukemia can result in the onset of unconjugated hyperbilirubinemia, potentially exacerbating the condition." (PMID 38651155, 2024).
prostate carcinoma (4 papers, 2016 to 2023). A carcinoma that arises from epithelial cells of the prostate gland. "The UGT1A1 gene is implicated in the development of several cancer subtypes, including colon, breast, and prostate cancer." (PMID 37759556, 2023). "Two studies on Caucasian populations have investigated the association between UGT1A1 promoter region polymorphism (TA)n and prostate cancer risk." (PMID 27074016, 2016). "Thus, the association between UGT1A1 genotype and prostate cancer in Afro-Caribbean men must be interpreted with care, as the possibility of a chance association cannot be ruled out." (PMID 27074016, 2016). "We investigated whether functional polymorphisms of CYP17, CYP19, CYP1B1, COMT and UGT1A1 affected the risk of prostate cancer in two different populations of African ancestry." (PMID 27074016, 2016).
breast tumor (3 papers, 2005 to 2026). "Furthermore, because a common competing metabolic pathway for SULT1A1-mediated sulfation of estrogens is UGT1A1-mediated glucuronidation of E2, we also hypothesized that UGT1A1 alleles might represent modifiers of breast tumor characteristics." (PMID 16280036, 2005). "We also showed that UGT1A1 mRNA is significantly decreased in breast tumors compared to normal breast tissues." (PMID 30349745, 2012). "The finding of a significant decrease of UGT1A1 mRNA levels in breast tumor specimens from postmenopausal women suggests that UGT1A1 may play a vital role in estrogen conjugation." (PMID 30349745, 2012). "In the present study, we characterized the mRNA expression of UGT1A1, UGT1A4, UGT1A8, UGT1A10, and UGT2B7 in normal and breast tumor tissues from AA and EA women." (PMID 30349745, 2012).
colon adenocarcinoma (3 papers, 2010 to 2022). "The isothiocyanate, sulforaphane and the flavonoid, epigenin increased gene expression of phase II detoxifying enzyme such as glutathione S-transferase (GSTA1) and UDP-glucuronosyltransferase (UGT1A1) in human colon adenocarcinoma." (PMID 24559113, 2014). "The influence of these TFs upon UGT1A1 transcriptional activity was then demonstrated by transient transfection in colon adenocarcinoma cell line HT29, and solely HNF1-alpha and USF1/2 have been shown to have significant impact." (PMID 20096102, 2010).
head and neck cancer (3 papers, 2016 to 2022). A primary or metastatic malignant neoplasm affecting the head and neck. "The UGT1A1 enzyme is an important UGT involved in the detoxification of tobacco smoke carcinogens, like benzopyrenes and genetic polymorphisms in UTG1A1 are associated with the risk of head and neck cancer." (PMID 26751466, 2016).
Hepatitis (3 papers, 2013 to 2023). Inflammation of the liver. "The post-hepatitis group showed a significant difference in the UGT1A1*28/*6 allele gene frequency distribution relative to that in the hepatitis control group." (PMID 29386646, 2018). "Homozygous TA insertion in the TATA box of the promoter region (UGT1A1*28) (14%) and homozygous UGT1A1*6 (11%) were frequently seen in the post-hepatitis patient group." (PMID 29386646, 2018). "The frequency of UGT1A1*28 wild/UGT1A1*6 wild, UGT1A1*28 wild/UGT1A1*6 hetero, UGT1A1*28 hetero/UGT1A1*6 hetero and UGT1A1*28 hetero/UGT1A1*6 wild also presented with a similar pattern between post-hepatitis patients and GS patients." (PMID 29386646, 2018). "Six different sub-genotypes based on UGT1A1*28 combined with UGT1A1*6 were detected in post-hepatitis patients (n = 70), and there were 5 subtypes seen among the hepatitis control group patients." (PMID 29386646, 2018). "However, with the few hepatitis A, D, or E virus-infected cases encountered, liver failure coincided with the UGT1A1 wild-type host; nevertheless, a detailed investigation is essential." (PMID 38028601, 2023). "Among the hepatitis-control patients, none were homozygous for the UGT1A1*6 genotype, and only one was homozygous for the UGT1A1*28 genotype." (PMID 29386646, 2018).